AR (androgen receptor)
Diseases named in the same sentence as AR in open-access papers (continued):
Sharing a sentence is not in itself a finding about the gene and the disease.
cancer (continued). "Castration-resistant prostate cancer (CRPC) is the advanced stage of cancer wherein AR is still a key player." (PMID 36831540, 2023). "The work presented in this study highlights the importance of maximising the suppression of AR signalling using combinatorial approaches to achieve better control of cancer growth." (PMID 37673961, 2023). "In PCa cells, cdk5 promotes cell growth in an androgen receptor- independent way and stimulate cancer progression." (PMID 37000265, 2023). "In sum, androgen/AR axis has an undeniable role in these cancers and future investigations are needed to clarify the intracrinology in these tumors and their related TME." (PMID 36941697, 2023). "A low level of PSAP immunostaining was also associated with high androgen receptor levels in both ERG-negative (p < 0.0001) and ERG-positive cancers (p < 0.0001)." (PMID 37892063, 2023). "AR-dependent cancer growth stimulation is also mediated by the suppression of anti-tumoral pathways." (PMID 37626654, 2023). "Several groups have shown that the androgen receptor (AR), an important oncogenic driver of PCa, promotes mitochondrial respiration in these cancer cells to sustain their aberrant proliferation." (PMID 37086156, 2023). "Considering that the main targets for this subtype of cancer are aromatase, ER, and AR, the effects of CBD plus AIs were investigated in these targets." (PMID 37173983, 2023). "The first small molecule-based PROTAC with a non-steroidal AR ligand as a target protein ligand and nutlin as an E3 ligase ligand via a PEG-based linker, reported in 2008, effectively degraded AR after cell membrane permeation in cancer cells." (PMID 37489365, 2023). "In PCa, the androgen receptor (AR) plays a crucial role in supporting the metabolic and biosynthetic demands of cancer cells." (PMID 37958610, 2023). "Luciferase reporter assay was conducted to examine the translation activity of GPX4 promoter, and immunohistochemistry (IHC) was conducted to analyze the levels of c-MYC, Ki-67 and AR in TQB3720-treated cancer tissues." (PMID 36744249, 2023). "Together, these data suggest that the anti-cancer PCa cell growth effects of UA is through its inhibition of RORγ function in control of AR-signaling pathway." (PMID 37180705, 2023). "In cancer cells, AOH at a dose of 10 μM caused the highest increase in the expression of AR as compared to the control and the DHEA treatment (*** p < 0.001)." (PMID 37298472, 2023). "Overall, our results validate that Pax5 is preferentially expressed during the AR-independent NE-like cancer progression." (PMID 38168280, 2023). "ERβ protein in female cancer specimens also revealed a direct association with PGR (r = 0.765; P< 0.0001), whereas both inversely linked with AR (r = -0.607 and r = -0.537, respectively; P< 0.0001 for both)." (PMID 37206439, 2023). "In Metastatic carcinomas, AR and ER positivity was seen in 100% while PR was positive in 75% of the cases." (PMID 37725629, 2023). "In upper urinary tract urothelial cell carcinoma (UUTUC), the presence of AR in the CSC (cancer stem cell) population increased cell clonogenicity, in vitro spheroid formation, and changed the miRNA profile." (PMID 35163477, 2022). "We validated the existence of the identified resistant cell populations in the investigated material by orthogonal AR staining, demonstrating the androgen receptor activity of cancer cells after ADT." (PMID 36115838, 2022). "The co-expression of AR signalling and NE biomarkers in the same cancer cells supports a “trans-differentiation” mechanism by which existing AR-positive PCa cells undergo de-differentiation by ARPIs and gain an NE lineage." (PMID 35832549, 2022).
cancer (continued). "We have previously reported that patients whose cancer has progressed while on BAT appear to have enhanced clinical responses to subsequent AR inhibition." (PMID 36194476, 2022). "Although androgen deprivation therapy, anti-androgen receptor (AR) therapy, and taxane-based chemotherapy are effective for advanced types of cancers, many patients with PC develop a more lethal form of PC called castration-resistant PC (CRPC)." (PMID 36263200, 2022). "The mechanisms of AR in these cancers are complex and dynamic, and require the cooperation of many coregulators which are not all identified." (PMID 35886904, 2022). "SREBP1 promotes cancer cell proliferation, migration, and invasion through transcriptional regulation of androgen receptor (AR) gene expression." (PMID 35163079, 2022). "In CRPC cells 22Rv1, cancer cell-specific new smaller TADs were identified at AR gene locus, and this alteration was believed to contribute to the exotic expression of AR-V7 in 22Rv1." (PMID 35966880, 2022). "Expression of the AR gene is also positively related to the survival of cancer patients, especially male cases." (PMID 36013056, 2022). "In fact, NCOA2 is able to reprogramme AR signalling in cancer cells towards metabolism for survival from therapy, while NCOA3 drives proliferation and promotes survival pathways to combat the activation of apoptosis." (PMID 37435460, 2022). "Taken together, these studies indicate that AR and ER have promising roles in the management of cancers including HNC." (PMID 35517428, 2022). "A recent pan‐cancer study revealed that AR is overexpressed in GBM, and few studies explored AR as a possible treatment target." (PMID 35661403, 2022). "Trials based on PROTAC molecules demonstrated the first clinical proof-of-concept against two of the most relevant cancer targets: the estrogen receptor (ER) and androgen receptor (AR)." (PMID 36077640, 2022). "Taken together, the combination of tautomycin and enzalutamide synergistically inhibited AR signaling activity, thereby reducing cancer cell proliferation." (PMID 36446767, 2022). "In conclusion, AR-mediated predisposition for CD8 + T cell exhaustion interferes with eliminating nascent immunogenic malignant cells, leading to a male bias in cancer incidence and mortality." (PMID 36273184, 2022). "Numerous tRFs have been shown to be abundantly expressed in estrogen receptor-positive breast cancer and androgen receptor-positive prostate cancer and to enhance cancer cell proliferation." (PMID 35961977, 2022). "In contrast, AR signaling inhibition reprograms CD8 + T cells into a stem cell-like state to potentiate cancer immunotherapy." (PMID 36273184, 2022). "AR-targeting therapies have been investigated for their potential therapeutic use in the treatment of AR+ cancers." (PMID 35618789, 2022). "ARNEG cells can be classified as either neuroendocrine (NE), small-cell features (SCNPC), or double negative (DNPC) that lack both NE markers and AR, whereas ARPOS cancer cells can show either high (ARPC) or low AR expression (ARLPC)." (PMID 36561929, 2022). "Surprisingly, for most of the CPRC patients, cancer growth still depends on androgen receptor signaling." (PMID 35966880, 2022). "The praecox and long-term use of potent AR inhibitors can induce adaptive phenotypes in cancer cells through the activation of both AR-dependent and AR-independent survival pathways." (PMID 35406564, 2022). "The miRNA signatures of AR-negative cancers were similarly expressed in QNBC, and miRNA expression within AR-positive cases was associated with luminal A/B and TNBC AR-positive cases." (PMID 36550153, 2022). "In this report, we uncover a dual-modified AR engendered by cancer cells to maintain high AR and ACK1, overcoming the effect of AR antagonists." (PMID 35704598, 2022).
cancer (continued). "Two other major cell types within the cancer microenvironment are endothelial cells and immune cells, though the role of AR within these cell types is less well understood." (PMID 37435460, 2022). "The expression of the CAF-related marker genes for activated phenotype for cancer-associated fibroblast SDF1, FAP, αSMA, and the androgen receptor were inconsistently deregulated in the six analyzed paired samples." (PMID 35740605, 2022). "Within the context of HCC, transcriptomic analyses of 24 HCC cell lines from the Cancer Cell Line Encyclopedia (CCLE) database revealed that higher AR expressing cell lines were enriched for expression of EMT-related genes." (PMID 36430245, 2022). "PRKDC can drive cancer progression by interacting with androgen receptor or estrogen receptor to mediate transcriptional regulation." (PMID 35468873, 2022). "To study metabolic changes related to cancer stem cells and therapy resistance we developed a cell line resistant to the androgen receptor and chemotherapeutic 2-hydroxyflutamide." (PMID 36325358, 2022). "Targeting the androgen receptor (AR) by medical castration or target therapy results in a regression of the cancer, but eventually cancer cells will gain androgen independence, resulting in a relapse of the cancer." (PMID 36139541, 2022). "These cancers lose AR signaling, become more aggressive and exhibit androgen-independence in a quite scantly known molecular landscape." (PMID 35222290, 2022). "It is possible that AR promotes the progression of this type of cancer through controlling the expression of miRNAs that are crucial for BC development, such as miR-125b, miR-21, and let-7a." (PMID 35163477, 2022). "Numerous studies have shown that AR regulated the progression of cancer stem cells in various cancer types, including OVCA." (PMID 35886904, 2022). "In Proteoglycans in cancer related pathway, the expression level of Twist was elevated which is one of the transcriptional factor in AR expressing cell." (PMID 34983378, 2022). "About invasive luminal cancers, we found a potential role of AR/PgR ratio > 0.96 in predicting the efficacy of first-line endocrine treatment in HR+ advanced BC." (PMID 36111296, 2022). "The combination of ADT and hypoxia can induce adaptive androgen receptor signalling and/or development of AR-independent cancer cells." (PMID 35493092, 2022). "The immunohistochemical analysis of the resected bone metastases identified the PSA and AR positive cancer cells, similar to the result of lymph node metastases." (PMID 35183184, 2022). "Src-mediated AR Tyr-534 phosphorylation is known to induce AR nuclear translocation, active its transcriptional activity, and drive cancer cell growth in response to EGF stimulation." (PMID 35595729, 2022). "Targeting AR signalling in the long-term is predictably ineffective since it blocks one cancer cell population and permits others to expand." (PMID 35832549, 2022). "Worthy of note, FOXA1 mRNA and protein levels are also closely related with those of AR in hormone-dependent cancer models." (PMID 36230619, 2022). "In turn, in patients with CRPC cancer, nuclear protein expression was found in 94% of the cases, which additionally correlated with the expression of AR-FL (full-length androgen receptor)." (PMID 35055079, 2022). "In terms of histology, crude analysis showed type I cancers were more frequent in AR-positive group (OR = 2.393, 95% CI = 1.789–3.202, P < 0.001)." (PMID 35814433, 2022). "In a mouse model of type I EC, a third-generation AR antagonist, enzalutamide inhibited EC cell proliferation and increased cancer cell apoptosis in a dose-dependent manner." (PMID 36358974, 2022).
cancer (continued). "For example, the prostate as an androgen-dependent organ can progress into hyperplasia and even cancer by excessive activation of AR." (PMID 36362304, 2022). "Similar to the miR-99b-5p effect on mTOR expression/location, the AR expression levels were significantly reduced in miR-99b-5p mimic vs. NS transfected cancer cells (total lysates)." (PMID 36077039, 2022). "For example, AR can constitute part of enhanceosomes, hence overactivation of transcription in cancer should also be studied in the contexts of liquid-like phase separated condensate-state." (PMID 36388907, 2022). "Consistently, androgen depletion or AR-pathway inhibitors (ARI) derepressed IL1β in AR-positive cancer cells, both in vitro and in vivo." (PMID 36561929, 2022). "While this effect was more pronounced in basal cell-derived cancer organoids, both organoid lines were able to form and grow out under the presence of the androgen receptor inhibitor enzalutamide." (PMID 35159020, 2022). "Studies using in vitro cell models indicated that the ligand-dependent and ligand-independent AR signalling, and AR bypass mechanisms can all be possibly adopted by cancer cells." (PMID 35832549, 2022). "At later stages of cancer development, epigenetic changes seem to reprogram the AR transcriptome, presumably by activating developmental processes and AR binding sites that have a role in prostate organogenesis." (PMID 36551650, 2022). "Although little is known about the exact mechanism, AR is presumed to be related to glucose metabolism in cancer cells, as well as normal tissues." (PMID 36178912, 2022). "Taken together, all evidence supports that the way epithelial AR interacts with chromatin, and regulates genes, alters with cancer progression." (PMID 37435460, 2022). "In malignant cells, the target AR gene group is known to be involved in the onset and progression of cancer." (PMID 35456428, 2022). "Given that some small chemical molecules exhibit stronger lipophilicity, Crews’ group developed the first small-molecule based PROTAC in 2008 to effectively degrade AR in cancer cells." (PMID 35410300, 2022). "Lehmann’s group showed that AR enriched TNBC cell lines carrying PI3KCA mutations acquire sensitivity to PI3K/mTOR inhibition, promoting cancer cell growth." (PMID 36111296, 2022). "The aim of this study is to determine the expression of AR and the proportion of AR positive cancers in TNBCs at the Lagos University Teaching Hospital, Lagos, Nigeria." (PMID 36405944, 2022). "For this reason the focus is now shifting to the chromatin modifying coregulator proteins such as lysine demethylases (KDMs) that are key cofactors for cancer drivers such as AR." (PMID 36263323, 2022). "Stromal AR is also important in cancer initiation, regulating paracrine factors that excite cancer cell proliferation, but lower stromal AR expression correlates with shorter time to progression/worse outcomes." (PMID 37435460, 2022). "This is consistent with results obtained in a previous study that performed a targeted AR sequencing in a cohort of 181 primary cancers and 37 CRPCs." (PMID 36176747, 2022). "These cancers lose the AR-dependent signaling and progress towards an aggressive phenotype, whose molecular drivers are still under investigation." (PMID 35222290, 2022). "Expression and activity of AR are highly elevated in castration-resistant PCa to enable cancer cells to gain the advantages of growth, survival and invasion." (PMID 35386201, 2022). "We previously reported, in older patients, a high rate of mucinous and apocrine cancers and higher rates of GCDFP-15 and AR-positive cancers." (PMID 36553136, 2022).
cancer (continued). "Using a photo-pTyr-scaffold screen, we have found that Kindlin-2 regulates AR Tyr-534 phosphorylation, an event that is critical for AR activation, downstream signaling, and cancer progression." (PMID 35595729, 2022). "Findings from clinical, pharmacological, and genetic studies have now converged to demonstrate an important role of AR in these cancers." (PMID 35886904, 2022). "ARV-110 inhibited the synthesis of prostate-specific antigen (PSA) and AR-dependent cancer cell proliferation by inducing apoptotic cell death." (PMID 36499765, 2022). "The identification of castration-resistant cancer populations in hormone naïve PCa opens up the possibility of early selection of men for non-AR directed therapies such as chemotherapy or PARP inhibitors." (PMID 36115838, 2022). "AR is expressed in 30–80% of BC, with more common co-expression with ER+ (70–90%) over ER– cancer (20–30%)." (PMID 36376977, 2022). "Basically, SB is reported to modulate invasion, migration and EMT phenotype in cancers through multiple mechanisms, such as AR signaling 62 and Wnt/β-catenin pathway." (PMID 36313039, 2022). "Accordingly, reduction of AR in cells treated with the anti-cancer agent methaneseleninic acid (a seleninic acid with the chemical formula CH3SeO2H) has been associated with reduced hTERT expression in both wild type and AR-mutated cells." (PMID 35974340, 2022). "Meantime, the recovery of PSA secretion indicates that AR is reactivated in these cases, enabling cancer cells to respond to castrated levels of androgen." (PMID 36362304, 2022). "More recently, AR signaling in the cancer stroma was shown to impact patient outcomes by inhibiting cancer cell invasion, however, the mechanisms behind the roles stromal AR plays in disease progression are not fully understood." (PMID 36551674, 2022). "At the metastatic stage (mCRPC), the molecular landscape is rewired for AR independence, when cancer cells reduce AR activity and often decrease or turn off AR expression." (PMID 36561929, 2022). "Using DESEQ2 analysis of TCGA to reveal miRNA signatures of AR-negative versus AR-positive cancers, we identified 45 miRNAs that were differentially expressed and clustered by AR status and subtype." (PMID 36550153, 2022). "Accordingly, ART disrupted resistance in other cancer types that have become insensitive to conventional therapeutic agents, including bicalutamide, an androgen receptor antagonist, applied formerly to treat metastatic castration-resistant prostate cancer." (PMID 35198441, 2022). "Studies found that prostate cancer gene expression marker 1 (PCGEM1) with highly prostate-specificity was also related to androgen receptor (AR) signaling and was overexpressed in therapy-resistant PCa." (PMID 36514044, 2022). "For example, the clinically actionable gene AR was significantly changed at the mRNA and protein levels in 10 cancer types, including PRAD." (PMID 36289218, 2022). "AR signaling is a cornerstone of PCa progression and AR-targeted therapy is one of the most successful targeted therapies in cancer treatment." (PMID 36300093, 2022). "As AR action in non-cancer cells is a developing area of research, the role of coregulators in cells of the microenvironment such as smooth muscle cells, fibroblasts, other mesenchymal cells, and immune cells needs to be understood." (PMID 37435460, 2022). "The microenvironment is composed of many different cell types, here, we will review AR in the main constituents of the cancer microenvironment; smooth muscle, fibroblast, endothelial, and immune cells." (PMID 37435460, 2022). "Decreased AR activity downregulates the factors that protect cancer cells from DNA damage, including PARP proteins, which then become cancer cell-selective combinatorial lethal targets." (PMID 35164752, 2022). "It suggests that BORIS affect OVCA process by regulating proliferation and apoptosis of cancer cells through AR." (PMID 35886904, 2022).